METTL3 (methyltransferase 3, N6-adenosine-methyltransferase complex catalytic subunit)
Diseases named in the same sentence as METTL3 in open-access papers (continued):
Sharing a sentence is not in itself a finding about the gene and the disease.
cervical cancer (continued). "Based on these results, a model is strongly supported and proposed that METTL3 regulates cell sensitivity to cisplatin in cervical cancer possibly via inhibition of RAGE." (PMID 34514103, 2021). "A combination of bioinformatics algorithms, functional analyses, and xenograft models revealed the pivotal roles of METTL3/miR-193b/CCND1 signaling in cervical cancer aggressiveness." (PMID 34178650, 2021). "METTL3 promoted the stability of H2K through m6A modification, thereby promoting Warburg effect and the proliferation of cervical cancer cells." (PMID 33816306, 2021). "Two other studies demonstrated that METTL3 can enhance the growth of cervical cancer cells and promote tumorigenesis." (PMID 34514103, 2021). "Mettl3 has also been proven to promote the progression of cervical cancer, which is also a gynecological tumor." (PMID 34187307, 2021). "Silencing METTL3 in cervical cancer cells inhibited miR-193b levels and increased the expression of pri-miR-193b, suggesting that METTL3 modulated miR-193b mature process." (PMID 34178650, 2021). "Conclusions: iASPP and METTL3 levels were elevated in cervical cancer, and they were both independent indicators for poor prognosis in early stage cervical cancer patients." (PMID 32201509, 2020). "Here, we aim to explore the associations between the levels of METTL3 and CD33+ myeloid-derived suppressor cells (MDSCs) in tumour tissues and the survival of patients with cervical cancer (CC)." (PMID 33059689, 2020). "We then examined the protein level of iASPP and METTL3 in the samples from a cohort of 112 cervical cancer patients by immunohistochemistry." (PMID 32201509, 2020). "The luciferase assay showed that the promoter activities of Mettl3 in cervical cancer cells were significantly greater than that in ECT1/E6E7 cells." (PMID 32444598, 2020). "Our data showed that the protein and mRNA expression of Mettl3 increased in cervical cancer HeLa and SiHa cells as compared with that in ECT1/E6E7 cells." (PMID 32444598, 2020). "Using the online bioinformatics tools including GEPIA and Kaplan‐Meier plotter, we found that cervical cancer patients with increased expression of Mettl3 and TBP showed reduced disease-free survival (DFS)." (PMID 32444598, 2020). "iASPP and METTL3 were higher in cervical cancer than normal cervix samples (p<0.001 and p<0.01, respectively)." (PMID 32201509, 2020). "The results showed that both iASPP and METTL3 expression levels were higher in cervical cancer than normal cervix samples." (PMID 32201509, 2020). "Further, Mettl3 expression in cervical cancer tissues was significantly (p < 0.01) greater than that in normal tissues, according to Zhai Cervix, Biewenga Cervix, and Pyeon Muti-Cancer data from the Oncomine database." (PMID 32444598, 2020). "Further, the expression of TBP was significantly and positively correlated with the expression of Mettl3 in clinical cervical cancer patients from ChIPBase34, GEPIA, or TCGA database." (PMID 32444598, 2020). "We then questioned the possibility of a link between the METTL3/TGFβ1/Snail axis and the clinical development of cervical cancer." (PMID 31991845, 2020). "Further, TATA-binding protein (TBP) can transcriptionally increase the expression of Mettl3 in cervical cancer cells via binding to its promoter." (PMID 32444598, 2020). "After analyzing the tumor sizes and weight, the results showed that overexpression of METTL3 significantly potentiated allograft growth of cervical cancer in vivo, which increased both tumor sizes and tumor weight, confirming the cancer‐promoting role of METTL3 in cancer progression." (PMID 39535388, 2025). "In particular, METTL3 contributed to cervical cancer progression." (PMID 39856747, 2025). "METTL3 acts as a methyltransferase and participates in cervical cancer progression." (PMID 39856747, 2025). "METTL3 is an m6A “writer” protein that has been reported to promote cervical cancer progression." (PMID 39856747, 2025).
cervical cancer (continued). "The METTL3-dependent regulation of DLG2 mRNA stability could be a critical factor in cervical cancer progression." (PMID 39856747, 2025). "The upregulation of HDAC6 induced by METTL3 over‐expression is capable of inhibiting cilia elongation and acetylation of α‐tubulin, thereby shortening cilia length and accelerating the progression of cervical cancer both in vitro and in vivo." (PMID 39535388, 2025). "Moreover, DLG2 silencing attenuated METTL3 knockdown-induced effects in cervical cancer cells, indicating that the METTL3/DLG2 axis was involved in cervical cancer progression." (PMID 39856747, 2025). "We further analyzed whether DLG2 was involved in the regulation of METTL3 in the malignant phenotypes of cervical cancer cells." (PMID 39856747, 2025). "Furthermore, mortalin gained increased mRNA stability and enhanced translation efficiency via the m6A methylation in the HSPA9 mRNA 3’UTR, which was catalysed by METTL3 in cervical cancer cells." (PMID 40332203, 2025). "In addition, survival analysis showed that cervical cancer patients with increased expression of METTL3, YTHDF3, and HDAC6 represented an obviously unsatisfied overall survival (OS)." (PMID 39535388, 2025). "Moreover, lowering DLG2 expression mitigated the effects of METTL3 silencing on cervical cancer cell malignancy." (PMID 39856747, 2025). "In our study, we found that inhibition of METTL3 could significantly restore ciliation in cervical cancer cells, which was characterized by increased elongation of cilia length via inhibiting HDAC6 expression." (PMID 39535388, 2025). "Taken together, cervical cancer progression involved a high METTL3 expression, and the elevated METTL3 expression reduced DLG2 release in an m6A-dependent manner to activate the Hippo/YAP pathway, further promoting tumor cell proliferation, migration and invasion and inhibiting cell apoptosis." (PMID 39856747, 2025). "Similarly, miR-30c-5p promotes the ferroptosis of cervical cancer by targeting the METTL3/KRAS axis, and inhibits the growth and metastasis of xenografts of cervical cancer." (PMID 38550378, 2024). "METTL3 participates in the mRNA stability of Rab2, promoting the growth of cervical cancer cells." (PMID 36976668, 2023). "METTL3 was upregulated in cervical cancer (CC) tissue and cells, and high levels of METTL3 could predict poor prognosis of CC patients." (PMID 36835633, 2023). "In cervical cancer, it is elucidated that METTL3 could promote pri‐miR‐193b m6A level and processing." (PMID 36162823, 2023). "The expression of METTL3 is significantly increased in the M-phase of cervical cancer cells." (PMID 37996892, 2023). "The enzymes METTL3, METTL14, and others are responsible for catalyzing the methylation process on RNA, and recent investigations have uncovered the role of METTL3, a methyltransferase-like 3 enzyme, in contributing to the Warburg effect exhibited in cervical cancer (CC)." (PMID 38202657, 2023). "Furthermore, high levels of METTL3 and YTHDF1 expression in cervical cancer patients were linked to a poor prognosis." (PMID 36091006, 2022). "Furthermore, using an immunochemistry assay, we showed that the protein expression of METTL3 was related to CDC25B expression in cervical cancer specimens." (PMID 35637959, 2022). "METTL3, acting as the core component of N6-methytransferse complex, has been reported to be involved in a variety of tumor biological progression, including cervical cancer." (PMID 36566195, 2022). "METTL3/FOXD2-AS1 accelerated cervical cancer progression via an m6A-dependent modality." (PMID 36058934, 2022). "Interestingly, elevated expression of METTL3 is associated with regulation of MDSC differentiation and poor prognosis of cervical cancer." (PMID 35794625, 2022). "The expression of METTL3 is correlated with the expression of CDC25B in cervix cancer." (PMID 35637959, 2022).
cervical cancer (continued). "The key finding of this study was that m6A regulator METTL3 was associated with tumor HPV status and HPV expression, and METTL3 high status facilitated the formation of an immunosuppressed tumor microenvironment and targeting METTL3 promoted immunotherapy in HPV-related cervical cancer." (PMID 35813476, 2022). "Taken together, these data indicated that METTL3 could increase the sensitivity to cisplatin in cervical cancer cells." (PMID 34514103, 2021). "In addition, as compared to the ECT cell line, the expression level of METTL3 was significantly decreased in multiple cell lines of cervical cancer, except in the C33A cell line." (PMID 34514103, 2021). "Furthermore, METTL3 overexpression inhibited viability and increased cisplatin sensitivity of cervical cancer cells in vitro." (PMID 34514103, 2021). "Taken together, these results strongly supported that METTL3 could increase the sensitivity to cisplatin via downregulating RAGE in cervical cancer cells." (PMID 34514103, 2021). "However, several questions need to be addressed to fully understand the role of METTL3 in cervical cancer." (PMID 34514103, 2021). "Therefore, the role of METTL3 in the regulation of cisplatin sensitivity in cervical cancer cells was determined." (PMID 34514103, 2021). "METTL3 inhibits the growth of cervical cancer cells both in vitro and in vivo." (PMID 34514103, 2021). "RIP assays were used to further discover the role of METTL3 in cervical cancer." (PMID 34178650, 2021). "METTL3 is a novel tumor suppressor in cervical cancer tumorigenesis and progression." (PMID 34514103, 2021). "Interestingly, there have been several studies concerning the role of METTL3 as an oncoprotein in cervical cancer." (PMID 34514103, 2021). "Finally, we found that TBP can regulate the transcription of Mettl3 to increase its expression in cervical cancer cells." (PMID 32444598, 2020). "All these data suggested that TBP might be responsible for the upregulation of Mettl3 in cervical cancer cells via binding to its promoter-proximal site to increase the transcription." (PMID 32444598, 2020). "In conclusion, both iASPP and METTL3 protein expression levels were elevated in cervical cancer." (PMID 32201509, 2020). "The expression of Mettl3 was positively correlated with the PDK4 mRNA in cervical cancer patients." (PMID 32444598, 2020). "In addition, the precursor mRNA of Mettl3 in cervical cancer cells was also greater than that in ECT1/E6E7 cells." (PMID 32444598, 2020). "It indicated that the transcription of Mettl3 was activated in cervical cancer cells." (PMID 32444598, 2020). "Thus, METTL3 might promote the malignant progression of cervical cancer cells by decreasing DLG2 expression." (PMID 39856747, 2025). "Thus, DARS-AS1 might be required for the modulation of METTL3 in the DLG2/Hippo/YAP signaling in cervical cancer progression." (PMID 39856747, 2025). "Similarly, another study indicated that METTL3-mediated m6A modification on HK2 could accelerate the Warburg effects in cervical cancer." (PMID 36566195, 2022). "Therefore, METTL3 is an important promoting regulator of cisplatin sensitivity for cervical cancer." (PMID 34514103, 2021). "Therefore, we determined whether METTL3 could target the expression of RAGE in cervical cancer cells, leading to the regulation of cisplatin resistance." (PMID 34514103, 2021). "Therefore, further investigation is required to determine the role of METTL3 in cervical cancer." (PMID 34514103, 2021). "Taken together, METTL3 could suppress the expression of METTL3 in cervical cancer cells." (PMID 34514103, 2021). "Additionally, METTL3 reduced RAGE expression in cervical cancer cells." (PMID 34514103, 2021). "iASPP and METTL3 are independent prognostic factors for poor survival in early stage squamous cell cervical cancer patients, suggesting that iASPP and METTL3 might serve as novel potential prognostic markers and therapeutic targets for treatment of cervical cancer." (PMID 32201509, 2020).
cervical cancer (continued). "For example, METTL3 enhanced FOXD2-AS1 stability to promote the migration and proliferation of cervical cancer cells." (PMID 39856747, 2025). "In cervical cancer, quercetin potentiated cisplatin-induced apoptosis through coordinated downregulation of MMP2, METTL3, P-Glycoprotein (P-Gp), and ezrin." (PMID 40508204, 2025). "METTL3 maintained the mRNA stability of TXNDC5 to inhibit ER stress, further promoting cervical cancer cell metastasis." (PMID 39856747, 2025). "METTL3 modulates the expression of ULBP2 and affects the physiological function of cervical cancer cells." (PMID 40640957, 2025). "METTL3 was shown to be involved in UV-induced DNA damage response in U2OS (osteosarcoma) and HeLa (cervical cancer) cells, where elevated METTL3 recruitment was observed." (PMID 41369374, 2025). "We identified a novel mechanism by which METTL3 destabilized DLG2 expression to activate the Hippo/YAP pathway, thus promoting cervical cancer progression." (PMID 39856747, 2025). "Together, these results showed that both METTL3 and HDAC6 promote the progression of cervical cancer in vivo." (PMID 39535388, 2025). "Significantly, METTL3 also enhances the stability of HK2 mRNA through YTHDF1 mediated m6A modification, thereby promoting aerobic glycolysis in cervical cancer." (PMID 40097750, 2025). "Specifically, we found lower expression of METTL3, METTL14, and WTAP transcripts, while RBM15 and ALKBH5 abundance was elevated in cervical cancer cells." (PMID 38665783, 2024). "METTL3 can also affect the translation of CDC25B mRNA which will accelerate the process of cell cycle and promote the growth of cervical cancer cells." (PMID 38343637, 2024). "Further studies reported a remarkable m6A site in the 3’ UTR of FOXD2-AS1, and METTL3 overexpression upregulated the m6A modification level and FOXD2-AS1 stability in cervical cancer cells." (PMID 37069649, 2023). "METTL3 increases PDK4 RNA stability and translation to promote ATP production and glycolysis in cervical cancer cells." (PMID 37996892, 2023). "In conclusion, METTL3/FOXD2-AS1 accelerates cervical cancer progression in a m6A-dependent manner, suggesting a potential therapeutic target for cervical cancer." (PMID 37069649, 2023). "In cervical cancer, WDR5 was found to mediate H3K4me3 histone modification of the METTL3 promoter and induce METTL3 transcriptional activation." (PMID 37996892, 2023). "In cervical cancer cells, the transcription factor TBP binds directly to the promoter of METTL3 and upregulates METTL3 expression." (PMID 37996892, 2023). "Indicating that FOXD2-AS1 was positively regulated by METTL3, METTL3 maintained FOXD2-AS1 overexpression in cervical cancer." (PMID 37069649, 2023). "In accordance with the increased glucose turnover, overexpression of METTL3 is shown to increase the expression of various glycolytic enzymes in tumors including CRC and cervical cancer." (PMID 36289851, 2022). "Taken together, METTL3 and CDC25B expression are upregulated in human cervical cancer samples and the expression of CDC25B was related to that of METTL3." (PMID 35637959, 2022). "METTL3 enhanced the HK2 stability through YTHDF1-mediated m6A modification, thereby promoting the Warburg effect in cervical cancer." (PMID 36058934, 2022). "METTL3, METTL14, and WTAP methylation levels in cervical cancer were reported to be considerably greater than in surrounding normal tissues in a prior investigation." (PMID 36091006, 2022). "Some scientists have demonstrated that elevated expression of METTL3 promotes the proliferation of CD33+ MDSCs, leading to the progression of cervical cancer." (PMID 35864471, 2022). "In conclusion, our study demonstrates that METTL3 suppressed the activity of RAGE, thus increasing cisplatin sensitivity in cervical cancer." (PMID 34514103, 2021). "In this study, the expression levels of METTL3 and RAGE were detected in both cervical cancer cells and tissues." (PMID 34514103, 2021).
cervical cancer (continued). "The effects of METTL3 and RAGE on growth and cisplatin sensitivity were investigated in cervical cancer cells." (PMID 34514103, 2021). "Our results showed that METTL3 and RAGE were oppositely expressed in cervical cancer tissues, indicating the regulatory network between them." (PMID 34514103, 2021). "METTL3 inhibited cell viability and increased apoptosis as well as enhanced the sensitivity of cisplatin via downregulating RAGE expression in cervical cancer cells." (PMID 34514103, 2021). "The expression of Mettl3 in ECT1/E6E7, a human normal cervical epithelium cell line, and cervical cancer HeLa and SiHa cells were checked." (PMID 32444598, 2020). "On the other hand, knocking-down adenosine demethylases (FTO and ALKBH5) or overexpressing adenosine methyltransferases (METTL3 and METTL14) suppressed cervical cancer development in vivo." (PMID 29228737, 2017). "However, METTL3 and METTL14 have also been found to be both anti-oncogenic factors in cervical cancer." (PMID 39967906, 2025). "As a result, in line with the oncogenic role of the METTL3/HDAC6 axis, higher expression of both METTL3, YTHDF3, and HDAC6 was observed in tumor tissues when compared to the matched adjacent normal tissues from cervical cancer patients." (PMID 39535388, 2025). "For example, the METTL3/circSTX6/SPI1 feedback loop plays an important role in cervical cancer, and drug development targeting this loop is expected to be a new direction for cervical cancer treatment." (PMID 40458727, 2025). "Collectively, depletion of METTL3‐mediated m6A modification leads to abnormally elongated cilia via suppressing HDAC6‐dependent deacetylation of axonemal α‐tubulin, ultimately attenuating cell growth and cervical cancer development." (PMID 39535388, 2025). "METTL3 maintained HK2 stability via YTHDF1-mediated m6A, driving Warburg effect in cervical cancer." (PMID 39060874, 2024). "Additionally, IGF2BP3 mediates METTL3 to regulate the stability of RAB2B mRNA, thus promoting the proliferation of cervical cancer cells." (PMID 37298373, 2023). "For example, FTO, METTL3, and YTHDF1 could promote the progression and metastasis of cervical cancer and are potential biomarkers for the prognosis of cervical cancer." (PMID 35432630, 2022). "METTL3-induced m6A modification recruits m6A readers to stabilize hexokinase 2 (HK2) mRNA at the 3’ untranslated region, thus increasing HK2 expression and promoting the Warburg effect in esophageal carcinoma, CRC and cervical cancer." (PMID 36289851, 2022). "Moreover, METTL3 recruited YTHDF1 to enhance HK2 stability, thereby promoting the Warburg effect of cervical cancer." (PMID 34185971, 2022). "METTL3 targets the 3′-UTR of hexokinase 2 (HK2) mRNA to enhance HK2 stability in a YTHDF1-dependent manner, which promotes the proliferation and aerobic glycolysis of cervical cancer cells." (PMID 36008936, 2022). "Co-treatment with quercetin and cisplatin synergistically inhibits proliferation, migration, and invasion and enhances apoptosis in HeLa and SiHa human cervical cancer cells by weakening matrix metallopeptidase 2 (MMP2), ezrin, P-glycoprotein, and methyltransferase-like 3 (METTL3) expressions." (PMID 36430891, 2022). "Clinical data analysis showed that METTL3 and CDC25B were highly expressed in cervical cancer." (PMID 35637959, 2022). "Moreover, METTL3 suppresses the activity of RAGE, thus increasing the cisplatin sensitivity in cervical cancer." (PMID 34514103, 2021). "Tumor tissues from cervical cancer showed a nearly negative METTL3 staining but an intense positive staining of RAGE, which was opposite to those in the normal adjacent tissues." (PMID 34514103, 2021). "Relation among METTL3, miR-193b, and CCND1 in cervical cancer." (PMID 34178650, 2021). "In addition, potential agonists of METTL3 together with RAGE inhibitors should be explored and developed to treat cervical cancer in the future." (PMID 34514103, 2021).